RHOA (ras homolog family member A)
Diseases named in the same sentence as RHOA in open-access papers (continued):
Sharing a sentence is not in itself a finding about the gene and the disease.
retinal degeneration (3 papers, 2014 to 2022). Degeneration of the retina. "In addition, expression of ROK in the wild type background caused retinal degeneration (arrows), similar to the described retinal degeneration when overexpressing RhoA." (PMID 24587072, 2014). "As a crucial regulatory gene, RHOA appears in multiple studies of retinal degeneration or dystrophy in relation to other genes." (PMID 35409321, 2022). "We found that a selective RhoA activation is not able, by itself, to induce retinal degeneration, as retinas treated with CNFY do not show any abnormality." (PMID 27775019, 2016). "To narrow the search of possible molecular effectors of the retinal degeneration induced by CNF1, we took advantage of Yersinia pseudotubercolosis Cytotoxic Necrotizing Factor (CNFY), a toxin that selectively activates RhoA, but not Rac/Cdc4224." (PMID 27775019, 2016).
retinal detachment (3 papers, 2017 to 2023). An eye emergency condition which may lead to blindness if left untreated. "We have reported that the activation of RhoA increases by over 1.5-fold 2 h after retinal detachment in vivo." (PMID 37296606, 2023). "We have shown that the RhoA signaling pathway is activated after retinal detachment in vitro and in vivo;13–15,21 ROCK phosphorylates MLC directly and stimulates its downstream effector LIM kinase (LIMK), which in turn phosphorylates cofilin." (PMID 28660097, 2017). "In a porcine retinal detachment model, RhoA activity increased within hours after the detachment." (PMID 28671996, 2017).
Thrombocytopenia (3 papers, 2013 to 2022). A reduction in the number of circulating thrombocytes. "In line with this, enhanced endogenous binding of mutant vWF to GPIbα in patients with vWF disease-type 2B results in giant platelets and thrombocytopenia and was reported to be associated with dysregulation of the LIM kinase/cofilin pathway in MKs, together with upregulated RhoA signalling." (PMID 28643773, 2017).
ZIKV infection (3 papers, 2020 to 2024). "Indeed, functional blockade of RhoA by its inhibitor Rhosin39 suppressed AaVA-1-mediated enhancement of ZIKV infection in THP-1 cells." (PMID 31937766, 2020). "Only a few mRNA’s were downregulated, but notably, these included Rac1/RhoA, which are GTPases with known roles in maintaining a neural progenitor cell pool and neuronal development, that we have previously proposed may be relevant to ZIKV infection in the developing brain." (PMID 37022660, 2023).
abdominal aortic aneurysm (2 papers, 2022 to 2024). Enlargement and ballooning of the vessel that supplies arterial blood to the abdomen, pelvis and legs. "RhoA is required in vascular smooth muscle cells to inhibit MAP4K4 and prevent abdominal aortic aneurysm formation." (PMID 36207400, 2022). "Furthermore, silencing SDC4 has been shown to enhance abdominal aortic aneurysm formation and VSMC phenotypic switching through the RhoA/G-actin/MRTF-A pathway 32, providing evidence that SDC4 can regulate ROCK function and participate in vascular remodeling." (PMID 39659565, 2024). "Whether a small GTPase RhoA plays a role in the pathology of abdominal aortic aneurysm (AAA) has not been determined." (PMID 36207400, 2022).
acute lung injury (2 papers, 2014 to 2022). A condition of lung damage that is characterized by bilateral pulmonary infiltrates (pulmonary edema) rich in neutrophils, and in the absence of clinical heart failure. "Carvedilol possess multiple functions such as antioxidation and neuroprotection RhoA/ROCK is reported to participate in acute lung injury (ALI)." (PMID 35188451, 2022).
adenomyosis (2 papers, 2020 to 2024). The growth of endometrial tissue inside the muscular wall of the uterine corpus. "The overexpression of the Ras homolog family member A/Rho-associated coiled-coil-containing protein kinase (RhoA/ROCK) in adenomyosis cells has been linked to elevated local estrogen expression." (PMID 39595579, 2024). "Interestingly, this study noted that in healthy women, RhoA/ROCKI activity varied relative to the menstrual cycle phase but was increased permanently in women with adenomyosis." (PMID 32443784, 2020).
adrenocortical cancer (2 papers, 2020 to 2022). "In adrenocortical carcinoma cells, stimulation with vasopressin, through V1R promotes cell senescence via RhoA signaling." (PMID 35874817, 2022). "Two of the studies demonstrated that RhoA was negatively associated with AKT phosphorylation and cyclin D1 in both endothelial cells and KRAS-driven adrenocortical cancer cell lines." (PMID 32244355, 2020).
age (2 papers, 2019 to 2024). A temporal measurement of the time period elapsed since an identifiable point in the life cycle of an organism. "Due to its role in the regulation of vascular tone and structural proteins, the RhoA/Rho-kinase pathway is an important target in age-related vascular dysfunction and diseases." (PMID 38473847, 2024).
amyloidosis (2 papers, 2020 to 2023). A disorder characterized by the localized or diffuse accumulation of amyloid protein in various anatomic sites. "Additionally, remodeling of the epithelial adherens tight junctions, Fc γ receptor mediated phagocytosis in macrophages and monocytes, and RhoA signaling and its impact of cytoskeletal dynamics were unique and specific to amyloid pathology." (PMID 32854643, 2020).
Bardet-Biedl syndrome (2 papers, 2017). A ciliopathy with multisystem involvement. "In Bardet–Biedl syndrome, RhoA levels are upregulated but treatment of mutant cells with RhoA inhibitors restores cilia length and number as well as actin cytoskeleton integrity." (PMID 29312958, 2017). "Bardet–Biedl syndrome (BBS) proteins and the cytoplasmic dynein light chain, Tctex-1, inhibit and enhance actin polymerization, respectively 6, 39, but because these studies use either inhibitors of RhoA or the actin polymerization inhibitor, cytochalasin D, indirect effects cannot be excluded." (PMID 27634431, 2017).
Breast Invasive Carcinoma (2 papers, 2020). "From the TCGA-BRCA database, the RNA expression level of BNIP-2 is reduced by about 11% in Breast Invasive Carcinoma (TCGA-BRCA) tissues compared to normal tissues, while neither RhoA nor GEF-H1 has noticeable differences between cancer and normal samples." (PMID 32789168, 2020).
cerebrovascular diseases (2 papers, 2010 to 2021). "The establishment of the RhoA/p38MAPK signal transduction pathway provides the basis and method for preventing and treating cardiovascular and cerebrovascular diseases caused by various stress responses." (PMID 33763149, 2021). "Activation of the RhoA – Rho-kinase pathway has been recently implicated as a key signaling mechanism in the development of several cerebrovascular disorders." (PMID 21217826, 2010).
cognitive decline (2 papers, 2024 to 2025). "In summary, Lingo1 upregulation in hippocampal neurons might promote myelination inhibition or myelin sheath loss through the RhoA/ROCK1 pathway, which plays important roles in the occurrence and development of postoperative cognitive decline." (PMID 39781463, 2025). "Moreover, upregulated Lingo1 in hippocampal neurons contributed to cognitive decline after surgery through activating the RhoA/ROCK1 signaling pathway and inhibiting the EGFR/PI3K/Akt signaling pathway." (PMID 39781463, 2025). "Though, to determine the therapeutic potential of IH for cognitive decline, it needs to be established whether the upregulation of RhoA/ROCK pathway genes in the cortex acts to prevent maladaptive plasticity or induces a disease-like state." (PMID 38985935, 2024).
coronary artery spasm (2 papers, 2013 to 2019). "Remnant lipoproteins, acting via the RhoA/Rho-kinase pathway to cause coronary vasospasm are considered to be a major factor in sudden death in humans." (PMID 24059472, 2013). "Smoking-induced increase in coronary artery spasm is due to increased RhoA activity." (PMID 31174369, 2019).
cutaneous melanoma (2 papers, 2021 to 2022). A primary melanoma arising from atypical melanocytes in the skin. "Amplification of RhoA/C or MRTF-A/B or mutations in upstream activators of RhoA/C have been found in ≈30% cutaneous melanomas." (PMID 33921974, 2021).
dengue (2 papers, 2022 to 2025). "Our results align with previous studies demonstrating that targeting the RhoA pathway can reduce vascular permeability and improve outcomes during severe dengue, supporting the therapeutic relevance of modulating this pathway." (PMID 40821819, 2025).
Dyskinesia (2 papers, 2022 to 2025). A movement disorder which consists of effects including diminished voluntary movements and the presence of involuntary movements. "Related to this, the brain renin–angiotensin system (RAS) and the RhoA/Rho kinase (ROCK) pathway, which are involved in dopaminergic neurodegeneration in PD as key mediators of oxidative stress and neuroinflammation, are also involved in dyskinesia development." (PMID 41154463, 2025).
Ectodermal dysplasia (2 papers, 2021 to 2025). "Few somatic missense variants in the RHOA gene have been so far associated with Ectodermal dysplasia with facial dysmorphism and acral, ocular, and brain anomalies (MIM: # 618727), a neuroectodermal disorder for which no prenatal phenotype has been described." (PMID 41153384, 2025).
emphysema (2 papers, 2012 to 2019). "Immune‐related processes, cilium assembly and movement, proteolysis, apoptotic mitochondrial changes, neutrophil degranulation and RhoA/ROCK signalling play a role in the pathological process of emphysema." (PMID 31419013, 2019).
endotoxemia (2 papers, 2017 to 2024). "There are also studies that have shown that the RhoA/ROCK pathway is activated in other myocardial inflammatory conditions such as endotoxemia and the beneficial effects of inhibitors of this pathway on the course of this disease." (PMID 38540212, 2024).
familial Mediterranean fever (2 papers, 2020 to 2023). Familial Mediterranean fever (FMF) is an autoinflammatory disorder characterized by recurrent short episodes of fever and serositis resulting in pain in the abdomen, chest, joints and muscles. "Familial Mediterranean Fever (FMF) is caused by the phagocyte production of pyrin gain of function variants, which have a lower threshold for inflammasome assembly upon RhoA-PKN axis inhibition." (PMID 37787552, 2023).
Glomerular sclerosis (2 papers, 2016 to 2021). Accumulation of scar tissue within the glomerulus. "Recent studies have indicated that podocyte-specific deletion of Cdc42 in vivo, but not of RhoA or Rac1, leads to congenital nephrotic syndrome and glomerulosclerosis." (PMID 26986510, 2016).
HCMV infection (2 papers, 2021 to 2025). "Western blot analysis demonstrated increased RhoA expression in ΔmiR-US25-1-infected cells compared to WT HCMV at all time points, suggesting that miR-US25-1 targets RhoA during HCMV infection." (PMID 33824207, 2021). "Since an individual miRNA can potentially target hundreds of genes, we wanted to assess the role of miR-US25-1 specifically targeting RhoA during HCMV infection." (PMID 33824207, 2021). "To assess the ability of miR-US25-1 to downregulate RhoA expression in the context of HCMV infection, we used bacterial artificial chromosome (BAC) recombineering to generate a mutant virus lacking the miR-US25-1 hairpin in HCMV TB40E-GFP." (PMID 33824207, 2021). "Taken together, the data indicate that RhoA is a miR-US25-1 target during HCMV infection." (PMID 33824207, 2021). "RhoA has been implicated in regulating migration during HCMV infection (46, –, 49); however, the role of RhoA during HCMV latency has not been explored." (PMID 33824207, 2021). "A recent study pointed to a role for RhoA in immune signaling during HCMV infection." (PMID 33824207, 2021).
Hepatic steatosis (2 papers, 2019 to 2023). Steatosis is a term used to denote lipid accumulation within hepatocytes. "Collectively, our findings suggest that ANXA1 reduces the development of hepatic steatosis and the associated liver injury by inhibition of RhoA activity and restoration of IRS-1 signaling." (PMID 30972066, 2019).
infarction (2 papers, 2018 to 2020). A localised pathological necrosis of tissue resulting from obstruction of the blood supply usually by a thrombus, an embolus, or vascular torsion. "Infarction was associated with increased RhoA/ROCK activation as shown by enhanced RhoA translocalization from the cytosol to the membrane." (PMID 29119680, 2018).
ischemia reperfusion injury (2 papers, 2020 to 2022). Adverse functional, metabolic, or structural changes in ischemic tissues resulting from the restoration of blood flow to the tissue (reperfusion), including swelling; hemorrhage; necrosis; and damage from free radicals. "The present study investigated whether Rho-associated protein kinase (RhoA/ROCK) signaling pathway inhibitor simvastatin inhibits matrix metalloproteinase 2 (MMP-2) activity in a rat ischemia-reperfusion injury (I/Ri) model by inhibiting the RhoA/ROCK pathway and reducing MMP-2 mRNA levels." (PMID 36139129, 2022). "In animal model of ischemia-reperfusion injury, inhibitors of RhoA/ROCK signaling pathways demonstrate a cardioprotective effect, which is realized through the activation of MAPK and NFkB signaling pathways and a reduction in Bcl-2 levels, leading to a decrease in the apoptotic activity of cells." (PMID 33352947, 2020).
kidney (2 papers, 2017 to 2023). "Overexpression of RhoA had the opposite changes, suggesting that RhoA positively regulated prostate fibrosis and EMT." (PMID 37864185, 2023). "RhoA is a member of the Ras superfamily of small GTP-binding proteins, which has been demonstrated to contribute to profibrotic signaling and fibronectin production in diabetic kidney and interfering with VEGF-mediated endothelial cell function." (PMID 29214163, 2017).
Legionella infection (2 papers, 2015 to 2022). "Notably, Casp-11−/− macrophages exhibited significantly lower levels of RhoA activity during Legionella infection when compared to WT cells." (PMID 26686473, 2015).
lung adenoma (2 papers, 2015 to 2019). A benign, well circumscribed epithelial neoplasm that arises from the bronchus or the lung parenchyma. "To eliminate potential developmental effects of K-RasG12D and RhoA deletion during mouse development, as well as to achieve more robust RhoA deletion, we next used adenoviral mediated induction of lung adenomas to yield a sporadic tumor model." (PMID 26030593, 2015). "Our study of the relationship between RhoA, RhoC and K-Ras in murine lung adenoma formation sheds light on the broader subject of cellular signal transduction networks, and how signal redundancy and compensation in these networks can result in counterintuitive results when the network is modified." (PMID 26030593, 2015). "Moreover, we found that deletion of either RhoA or RhoC alone did not suppress K-RasG12D induced lung adenoma initiation." (PMID 26030593, 2015).
lung small cell carcinoma (2 papers, 2021 to 2022). "One is RhoA, an MM mutation-susceptible locus-derived protein, and another is vigilin, a lung small cell carcinoma marker." (PMID 36323745, 2022).
lymphedema (2 papers, 2020 to 2022). Excess fluid collection in tissues, causing swelling. "Our results not only advance the current understanding of molecular mechanisms contributing to valve morphogenesis in the lymphatic vasculature, but also identifies RhoA/ROCK as a potential therapeutic target for treatment of hereditary forms of lymphedema." (PMID 32510325, 2020). "We found that TGF‐β1 blockade also decreased the mRNA expression of non‐canonical signaling pathways, including RhoA, MAPK, Akt and NFκB, suggesting that both canonical and non‐canonical signaling pathways regulate responses to increased TGF‐β1 expression in lymphedema." (PMID 35652284, 2022).
mesothelioma (2 papers, 2017 to 2022). A usually malignant and aggressive neoplasm of the mesothelium which is often associated with exposure to asbestos. "Thus, because RhoA is involved in cell migration, its mutation may affect mesothelioma migration." (PMID 36323745, 2022). "Collectively, these findings indicate that activation of RhoA/ROCK signaling contributes to YAP hyperactivity in pleural mesothelioma and inhibitors of RhoA/ROCK could be used to suppress YAP activity and thereby decrease cell viability of mesothelioma cells." (PMID 28470935, 2017).
metastatic melanoma (2 papers, 2009 to 2016). A melanoma that has spread from its primary site to another anatomic site. "We have found that another effect of increased Src signaling in metastatic melanoma cells is to suppress RhoA activity, through Src-dependent phosphorylation and activation of one of Rho's negative regulators, p190RhoGAP." (PMID 19400942, 2009). "This work explores whether the effects of UV on DNA damage, motility, proliferation, and survival of human metastatic melanoma cells are mediated by the RhoA pathway." (PMID 26823948, 2016).
microcephaly (2 papers, 2020 to 2025). A congenital or acquired developmental disorder in which the circumference of the head is smaller than normal for the person's age and sex. "Furthermore, in addition to Citron kinase and RhoA, three members of Kinesin family, Kif20a, Kif20b, and Kif4 regulate neocortical NPC cytokinesis and mutations of these genes result in reduced cortical size with microcephaly." (PMID 32159512, 2020).
myelodysplastic syndrome (2 papers, 2020 to 2023). A clonal hematopoietic disorder characterized by dysplasia and ineffective hematopoiesis in one or more of the hematopoietic cell lines. "Case LYWS-1389 (Erica Swenson) had a concurrent diagnosis of myelodysplastic syndrome (MDS) and AITL with a shared TET2 mutation, and with DNMT3A and RHOA mutations additionally identified only in the AITL component involving the pleural fluid." (PMID 37500795, 2023).
myocarditis (2 papers, 2015 to 2024). Myocarditis is a condition that is characterized by inflammation of the heart muscle (myocardium). "The current studies determined if pharmacological inhibition of SP-signaling via its high affinity receptor, NK1R and downstream G-protein, Ras homolog gene family, member-A (RhoA), will be beneficial in viral-myocarditis." (PMID 25821814, 2015). "We anticipated that if SP/NK1R mediated pathogenesis of myocarditis is mediated via RhoA-signaling, RhoA levels will be elevated in EMCV-infected mice and RhoA inhibitors will inhibit pathogenesis of EMCV infection." (PMID 25821814, 2015). "We hence hypothesized that pharmacological inhibition of SP-signaling via its high affinity receptor, NK1R and/or downstream G-protein, Ras homolog gene family, member-A (RhoA), will be beneficial in viral-myocarditis." (PMID 25821814, 2015). "In the current studies, we examined whether blocking of NK1R-signaling (with aprepitant) or RhoA activity in vivo with fasudil will improve survival and prevent manifestations of myocarditis (as studied by echo and Doppler)." (PMID 25821814, 2015). "However SP/NK1R mediated pathogenesis of EMCV-induced myocarditis is not significantly mediated via RhoA-signaling." (PMID 25821814, 2015).
nephrotic syndrome (2 papers, 2018 to 2020). A collection of symptoms that include severe edema, proteinuria, and hypoalbuminemia; it is indicative of renal dysfunction. "As Rac1, Cdc42, and RhoA are implicated in the pathogenesis of nephrotic syndrome in mice and humans, we examined whether these Rho GTPases interact with PLCE1 in cultured podocytes." (PMID 32238860, 2020).
neuroendocrine tumors (2 papers, 2016 to 2019). "RhoA was also identified as suitable reference gene in neuroendocrine tumors of the lung, and in porcine skeletal muscle at 26 different developmental stages." (PMID 30809246, 2019). "ACTB, CDKN1B, GAPDH, GRB2, RHOA and SDCBP are potent reference genes in neuroendocrine tumors of the lung." (PMID 27802291, 2016). "In the present study, ACTB, CDKN1B, GAPDH, GRB2, RHOA and SDCBP were identified as suitable reference genes in neuroendocrine tumors of the lung." (PMID 27802291, 2016).